CD276 (CD276 molecule)
Diseases named in the same sentence as CD276 in open-access papers (continued):
Sharing a sentence is not in itself a finding about the gene and the disease.
tumor (continued). "Our results showed that NK cells could recognize CD276+ tumor cells through CD16+, but their killing function was limited in NCT." (PMID 39076970, 2024). "Bicistronic CARs (BiCisCAR) targeting both FGFR4 and CD276, containing two distinct co-stimulatory domains, have superior prolonged persistent and invigorated anti-tumor activities compared to the optimized FGFR4-specific CAR and the other BiCisCAR with the same 4-1BB co-stimulatory domain." (PMID 39043633, 2024). "Collectively, the increased expression of CD276 in tumor tissue promotes tumor progression, and targeting CD276 might be able to prolong the survival time of patients." (PMID 39766794, 2024). "In contrast, further investigation into age, pathological grades, and tumor stages highlighted a clear pattern of differential CD276 expression; CD276 levels were notably higher in older patients, suggesting a potential age-related increase in expression (p<0.05)." (PMID 39319055, 2024). "DLD’s high expression may therefore reduce T cell-mediated anti-tumor immunity by regulating CD276 and immune checkpoints LAG3 positively and regulating CD8 + T cells’ immune infiltration." (PMID 38581529, 2024). "In addition, we found that the expression level of CD276 was related to tumor stage in ACC, BLCA, LIHC, LUAD, THCA, and OV." (PMID 39766794, 2024). "CD276 is overexpressed over a great variety of solid tumors, has limited expression in healthy tissues, and is not only expressed on tumor cells themselves but also on tumor vessels." (PMID 39367484, 2024). "Thus, CD276 is considered to be an attractive and promising tumor immunotherapy target, and plenty of related CD276-targeting drugs are currently undergoing or have completed clinical trials." (PMID 39766794, 2024). "CD276 is involved in tumor progression and affects the TME, making it more immunosuppressive." (PMID 39766794, 2024). "We analyzed tumor samples of 25 patients using immunohistochemistry to assess CD276 levels." (PMID 39367484, 2024). "In addition to the activation of NK cells, we specifically focused on the antigen recognition and cell killing of NK cells to CD276+ tumor cells." (PMID 39076970, 2024). "Immunoassay shows DLD’s high expression may reduce T cell-mediated anti-tumor immunity by regulating CD276 and immune checkpoints LAG3 positively and regulating CD8 + T cells’ immune infiltration." (PMID 38581529, 2024). "CD276, the target antigen of CC-3, is expressed on both tumor cells and tumor vessels of CRC." (PMID 38410109, 2024). "Depletion of CD276 leads to enhanced TAM MHCII expression, increased infiltration of cytotoxic CD8 + T cells, and reduced tumor growth in a mouse BLCA model, shedding light on the intricate mechanisms underlying tumor immune evasion." (PMID 38561369, 2024). "We hypothesized that combination treatment with anti-PD-1 antibody would thereby increase the capability of anti-CD276 antibody to elicit anti-tumor activity." (PMID 38561369, 2024). "Furthermore, to identify genes that were preferentially expressed in tumor-infiltrating T-cells expressing FGFR4.28HTM.28z-CD276.8HTM.BBz BiCisCAR, we performed a differential expression analysis." (PMID 39043633, 2024). "CD276 promotes epithelial-mesenchymal transition (EMT) and HCC invasion through the JAK2/STAT3/slug pathway and induces M2 polarization of tumor-associated macrophages (TAMs) to promote an immunosuppressive tumor microenvironment (TME) in a STAT3-dependent manner." (PMID 39640777, 2024). "Targeting CD276, which is expressed not only on tumors cells but also on tumor vessels, may serve to overcome this obstacle." (PMID 39367484, 2024). "In addition, the bladder indices, measured as ratios of bladder weight to body weight and BLCA tumor volume, were dramatically reduced after global KO of CD276." (PMID 38561369, 2024). "Subsequently, several current research revealed that CD276 played a co-inhibitory role in anti-tumor immunity, and could inhibit the proliferation of T cells." (PMID 38978106, 2024).
tumor (continued). "Previous investigations of CD276 mainly focused on its role in tumor cells." (PMID 38561369, 2024). "Univariate COX analysis revealed that the prognostic nutritional index, neutrophil‐to‐lymphocyte ratio, platelet‐to‐lymphocyte ratio, systemic inflammatory index, World Health Organization grading, tumor diameter, CD276 expression levels, T stage, and N stage were related to PFI (p < 0.05)." (PMID 39210603, 2024). "Newly conducted research has identified CD276 acts as a novel immune checkpoint molecule, a suppressor of T cells, and is directly involved in modulating the immune response and various malignant biological behaviors exhibited by tumor cells." (PMID 38339348, 2024). "Recent studies suggest that targeting immune checkpoints like CD276 in CSCs may enhance anti-tumor responses and inhibit metastasis." (PMID 39335624, 2024). "Given that cytotoxic CD8+ T cells are killer cells in the T lymphocyte population, this could explain the main tumor-promoting role of CD276 in cancer." (PMID 36717836, 2023). "Tumor cells express surface molecules associated with tumor immunity, especially immune checkpoints such as PD-L1, CTLA-4, and CD276, which play important roles in regulating antitumor immunity by costimulating or coinhibiting the killing effect of T cells and are thus key targets for immunotherapy." (PMID 37485079, 2023). "As an important immune checkpoint molecule, CD276 has a vital role in inhibiting T cell function, and because CD276 is highly expressed in most tumor cells, it may be a putative target for cancer immunotherapy in the future." (PMID 36717836, 2023). "At week 6, fLuc+ RD cells were still undetectable by bioluminescence in 3/5 CD276 mice, indicating a maintained complete remission, whereas in the other two CD276 mice the tumor growth was controlled until week 6, when bioluminescence measurements were stopped for technical reasons." (PMID 37924157, 2023). "CD276 promoted tumor metastasis by participating in epithelial mesenchymal transformation (EMT)." (PMID 36713082, 2023). "Assessment of the relationship between CD276 expression in tumor cells and clinical factors demonstrated its effect on lateral lymph node metastasis and postoperative serum CT levels, underscoring the need to identify effective therapies for patients with MTC and elevated CD276 protein levels." (PMID 37373167, 2023). "The high expression of CD276 in tumor tissues has generated interest among researchers." (PMID 37373167, 2023). "Bioinformatic analyses revealed five major cell types based on hallmark gene expression: myeloid (Cd11b; 12 clusters), lymphoid (Cd33/Ncr1/B220/Cd19; 5 clusters), tumor (Olig2/Cd276/Col11a1; 1 cluster), endothelial (Enpp2; 1 cluster) and fibroblast (plp1/Ptgds; 1 cluster) cells." (PMID 37333156, 2023). "Similar to the parent m276 mAb, this ADC demonstrates high-affinity binding to both human and mouse CD276 (KD 29 and 24 nM for hCD276 and mCD276, respectively) and, in preclinical tumor studies, displayed minimal toxicities at doses that proved highly efficacious." (PMID 38019654, 2023). "Several immune checkpoint genes (HAVCR2, CD47, LGALS9, and CD276) were gradually upregulated along the DC differentiation trajectory, especially at the late stage, revealing that C3-DC might suppress tumor immunity." (PMID 36788228, 2023). "In this pilot study, influenced by the past success of antibody-drug conjugates and tumor-targeted nanocarriers, fluorescently-labeled model micelles were modified with multiple anti-CD276 antibodies (CD276Ab), then tested for their efficiency in targeting tumor-derived cells." (PMID 37050422, 2023). "Abundant experimental evidence supports that CD276 affects tumor progression." (PMID 37373167, 2023). "Moreover, CD276 is also involved in tumor progression, metastasis, and poor clinical outcomes in various malignancies." (PMID 37830607, 2023).
tumor (continued). "Combining the HER2 CAR with GD2 CAR, CD276 CAR in combination with anti-CD47 antibody therapy may prove to be sufficiently potent to eradicate DIPG tumor cells in the brain and warrants further investigation." (PMID 37152812, 2023). "CD276 is involved in tumor immune evasion and tumor blood vessel formation." (PMID 38090056, 2023). "Furthermore, CD276 was reported negatively related to bleak prognosis as well as clinical outcomes of tumor patients with many kinds of cancer." (PMID 37159818, 2023). "Previous studies showed that CD276 could promote tumor immune escape, thus promoting the occurrence and development of tumors." (PMID 37006240, 2023). "Taken together, we disclosed the different immune characterization in two major and five rare DC subtypes, and revealed the unique profiles of four immune clusters, providing the potential managements of CD248 in the Cold tumor cluster and CD276/CAR-T in the Hot tumor cluster." (PMID 36991000, 2023). "Furthermore, a study on MGC018, an antibody-drug conjugate targeting CD276, showed effective antitumor activity in a variety of human tumor xenografts such as breast and lung cancers and favorable safety in animal models." (PMID 38260829, 2023). "One of the first examples of such a comprehensive analysis has been performed for an antibody-directed cytotoxic drug specific for B7H3/CD276, a tumor antigen that is expressed on a number of solid tumor types, and containing a pyrrolobenzodiazepine cytotoxic moiety." (PMID 37183816, 2023). "High expression of CD276 in the tumor vasculature may also contribute to the development of metastasis." (PMID 37373167, 2023). "Bioinformatic analyses revealed five major cell types based on hallmark gene expression: myeloid (Cd11b; 12 clusters), lymphoid (Cd33/Ncr1/B220/Cd19; five clusters), tumor (Olig2/Cd276/Col11a1; one cluster), endothelial (Enpp2; one cluster), and fibroblast (plp1/Ptgds; one cluster) cells." (PMID 37971169, 2023). "Also of potential significance regarding the tumour immune microenvironment, is the presence of two immune checkpoint genes, CD276 (also known as B7-H3) and NT5E (also known as CD73) in the set of 938 signature DEGs that separate the clusters." (PMID 36207323, 2022). "SRSF3 and CD276 have significant co-expression (P <0.05), and CD276 (B7-H3), as a possible immune checkpoint molecule, is predicted by researchers to become one of the most promising tumor immunotherapy targets." (PMID 35494088, 2022). "CD276 took part in the regulation of cell cycle, cell differentiation, proliferation, invasion, apoptosis, and epithelial-mesenchymal transition, and also participated in tumor metastasis." (PMID 36545327, 2022). "However, while tumors with high levels of tumor cell-associated NPs were found to have low TEC levels, the ratio of TECs with upregulated expression of CD276 and Plvap was found to be significantly higher." (PMID 36494816, 2022). "We therefore exclude this mode of CD276 regulation for the tumor lines investigated here." (PMID 35563359, 2022). "BiCisCAR T cells effectively eliminated tumor cells expressing GPC2 or CD276." (PMID 35852863, 2022). "CD276 is overexpressed in many pediatric solid tumors including NBs and tumor blood vessels." (PMID 35852863, 2022). "In particular, authors observed an improvement in cytotoxic T cells’ activation and interferon gamma (IFNγ) production under CD276 signal regulation, while a tumor escaping from immune cell surveillance was also identified by activating NFAT, NF-kB, and AP-1-related molecular pathways." (PMID 36555714, 2022). "Human B7-Homolog 3, B7-H3 (also known as CD276) is, in a cancer context, an immune checkpoint factor which may dampen the adaptive immune response to tumours." (PMID 36505819, 2022). "For example, a bispecific antibody that targets both PAUF and B7-H3 (also known as CD276) may generate a tumor specific but more potent anti-tumor effect." (PMID 36232715, 2022).
tumor (continued). "Given the heterogeneity of GPC2 and CD276 on NB cells, targeting only 1 antigen may be ineffective at eliminating the tumor, leading to immune evasion." (PMID 35852863, 2022). "We hypothesized that slow proliferating carcinoma cells may express CD276 at elevated levels, while in the metastases fast proliferating tumor cells are enriched." (PMID 35563359, 2022). "CD276 also could lead to increased NF-κB activity and elevated VEGF expression, further promoting tumor-associated angiogenesis and tumor invasion." (PMID 35211173, 2022). "In addition, we found that CD276 was highly expressed in the high-risk group, upregulated in HNSCC and helped tumor cells evade immune surveillance, consistent with our predicted results." (PMID 36406133, 2022). "High expression of the CD276 gene is thought to be associated with the development and metastasis of several cancers, and CD70 is involved in the survival of tumor cells and regulatory T cells through interaction with its ligand CD27." (PMID 35677427, 2022). "B7-H3 (CD276) has emerged as a target for cancer immunotherapy by virtue of consistent expression in many malignancies, relative absence from healthy tissues, and an emerging role as a driver of tumor immune inhibition." (PMID 36159778, 2022). "However, in the process of tumor development, CD276 can promote tumor invasion and metastasis and contributes to the resistance of anticancer drugs through various mechanisms." (PMID 35892678, 2022). "CD276 expression by the tumour vasculature is well established." (PMID 35884502, 2022). "Moreover, the results of the immune checkpoint analysis showed that NOL7 expression in most tumor tissues was positively correlated with C10orf54, CD276, IL12A, and especially HMGB1." (PMID 36077008, 2022). "CD276 is a checkpoint molecule involved in tumor immune evasion and metastasis." (PMID 35852863, 2022). "A previous study showed that miR-29c negatively regulates CD276 expression in tumor cells." (PMID 35514986, 2022). "In HCC, aberrantly expressed CD276 could promote tumor progression and inhibit the proliferation of CD8+ T cells." (PMID 35277569, 2022). "To model the heterogenous expression of GPC2 and CD276, which can result in tumor evasion in single-target CAR T cell therapies, we used a mixture of NALM6 cells stably expressing either GPC2 or CD276 and treated them with BiCisCARs or single antigen–targeting CARs." (PMID 35852863, 2022). "CD276 is a transmembrane glycoprotein overexpressed in both tumor cells and the tumor vasculature." (PMID 36276636, 2022). "However, the range of the CD276 score of benign samples surpassed the lowest quartile of the range of CD276 scores of the tumor samples (i.e., score 125) in only 3 of 47 cases (i.e., in 6.3%)." (PMID 33845814, 2021). "CD276, first identified in 2001 as a member of the B7 ligand family, is expressed by antigen-presenting cells, macrophages, and tumor cells, and has inhibitory effects on T-cells; these effects allow tumor cells to evade immune responses." (PMID 34680929, 2021). "Moreover, assessment of the relationship between CD276 expression in tumor cells and clinical factors demonstrated a weak but statistically significant positive correlation with tumor diameter (Spearman’s rank correlation coefficient = 0.31, p = 0.028)." (PMID 34680929, 2021). "On this basis, the system further correlated CD276 immunoreactivity to abnormal tumor vasculature." (PMID 33557152, 2021). "Furthermore, up-regulated CD276 promotes immune escaping of tumor cells, reducing the secretion of IFN-γ, tumor necrosis factor-alpha (TNF-α), and other cytokines." (PMID 33842369, 2021). "As CD276 expression level was observed to be correlated to tumor growth, invasion, and metastasis, CD276 could be a potential target for immunotherapy." (PMID 33842369, 2021). "Interestingly, CD276 labeling in the present study was strong in tumor vasculature, as expected, but not limited to it when using the Ventana automated tissue staining system." (PMID 33557152, 2021).
tumor (continued). "In contrast, in malignant tumor tissues CD276 expression levels are up-regulated." (PMID 33842369, 2021). "In order to investigate whether the PBK/CD276 axis plays an important role in tumor immune evasion, we conducted the cytotoxic T-lymphocyte assay." (PMID 33431797, 2021). "Genitourinary tumors provide a good example of elevated CD276 expression in tumor tissue." (PMID 33842369, 2021). "In comparison to PD-1 and CTLA-4 checkpoints, the mechanism of B7-H3 (CD276) in suppressing tumour development still remains unclear." (PMID 33995529, 2021). "Further bioinformatics analysis based on the TCGA database revealed that cluster analysis of tumor samples based on CD34/CD276 mRNA expression could well predict the survival status of patients." (PMID 34307389, 2021). "Our data suggest that CD276 on tumor cells is a significant contributor for macrophage recruitment." (PMID 34290311, 2021). "They found that CD276 CAR T cells control tumor growth in vitro and in vivo." (PMID 33842369, 2021). "Targeting CD276 with specific antibodies in our spheroid-macrophage coculture resulted in increased macrophage numbers in spheroids, suggesting that CD276 favors in our setting for tumor-supportive macrophage." (PMID 34290311, 2021). "However, to date there is no systematic study available investigating a possible role of CD276 on tumor in macrophage infiltration." (PMID 34290311, 2021). "In addition to its debated immune modulatory functions, CD276 gained considerable attention in the tumor field." (PMID 34290311, 2021). "Targeting CD276 directly on tumor cells is a promising strategy." (PMID 33845814, 2021). "Since CD276 is expressed on different cell types within the tumor, like differentiated as well as stem-like cells or even tumor vasculature, immunotherapy targeting B7-H3 may have great potential for complete tumor eradication." (PMID 33925968, 2021). "This suggests that the high expression of CD34/CD276 may promote a more complex tumor extracellular microenvironment, thus promoting the immune escape of CRC, which is consistent with the best KEGG pathway for GSEA enrichment analysis." (PMID 34307389, 2021). "However, a significant drop in the mean expression of CD276 was noted in the histologically normal tissue samples when stratified by the T stage of the tumor in the same specimen (< pT3a vs." (PMID 33845814, 2021). "During the crosstalk between tumor cells and MDMs, exchange of plasma membrane fragments—Trogocytosis36—might occur and tumor cells might acquire CD276 from MDMs." (PMID 34290311, 2021). "The T cell-suppressing immune check-point molecule CD276 (B7-H3) is highly expressed and may contribute to the immunoregulatory tumour milieu." (PMID 33669307, 2021). "So far, only a few findings identified revealed that overexpression of CD276 in tumor tissues was highly correlated with decreased expression of several miRNAs as compared to normal tissues, suggesting that a microRNA regulatory mechanism is involved in its differential expression." (PMID 33431797, 2021). "After CD276 is blocked with 8H9, anti-tumor effects are witnessed." (PMID 33842369, 2021). "It has also been shown that CD276 expression promotes migration and invasion of tumor cells." (PMID 34943606, 2021). "Moreover, a score ≥ 150 across 13 tumor types was observed for CD276, a clinically relevant ADC target." (PMID 33490264, 2021). "A recent study shows that CD276 is overexpressed by both cancer cells and the tumor vasculature." (PMID 34680929, 2021). "The specific task of mapping CD276 to a subset of blood vessels, and endothelial cells of abnormal tumor blood vessels in particular, can also be performed by a human observer, which is why this marker was chosen for machine recognition because a widely accepted feature is more convincing." (PMID 33557152, 2021). "In addition to its expression in the tumor vascular system, CD276 also affects the tumor microenvironment through microvessels in a soluble form (sB7-H3)." (PMID 33842369, 2021).